CD163 (CD163 molecule)
Diseases named in the same sentence as CD163 in open-access papers (continued):
Sharing a sentence is not in itself a finding about the gene and the disease.
tumor (continued). "This scenario highlights the fact that in the presence of a CD163+ population with such a direct negative effect on anti-tumor immune cells, treatment via the activation of effector cells would be difficult without either depleting CD163+ cells or reprogramming their immunosuppressive functions." (PMID 32899203, 2020). "Based on tumor purity, we ascertained that most cytokines are secreted by TAMs and M2 macrophages, and marker sets have significant correlations with CDH11 in STAD, with examples including CCL-2, TGFB1, CXCL12, and MPP2 of TAMs and IL-10, IL1R1, CD163, and MRC1 of M2 phenotype (P < 0.0001)." (PMID 32685527, 2020). "As recent studies indicated that infiltrated macrophages could affect the tumor progression, we then performed the immunofluorescence staining of 20 human NSCLC samples with antibodies to ERα and macrophage markers (CD68 and CD163) to examine their relationship in the microenvironment." (PMID 32356397, 2020). "The results showed that both CD163 and CD206 were expressed at a higher level in the peritumoral region than in the intratumoral region and normal liver tissues (p < 0.01), which indicated that the number of M2 macrophage was elevated in the tumor peripheral area." (PMID 33372604, 2020). "The main population of TAMs comprises CD163+ M2 macrophages, and CD163+ TAMs release soluble (s)CD163 and several proinflammatory chemokines (CXCL5, CXCL10, CCL19, etc.)as a result of TAM activation to induce an immunosuppressive tumor microenvironment together with other immunosuppressive cells." (PMID 32707850, 2020). "Indeed, stimulation of both TICs and LPMCs with IL-34 enhanced the expression of CD163 and CD206, typical markers of type 2 macrophages, a subset of cells that play critical roles in the promotion of tumor development, progression, metastasis, and therapeutic resistance." (PMID 33298879, 2020). "Interestingly, further analyses found that MCTC ratio was significantly associated with the expression of CD163 (r = 0.526, P < 0.001), but not with CD68 at tumor invasive front (r = 0.128, P = 0.256)." (PMID 30927925, 2019). "Nevertheless, a logistic regression analysis for the RMA and RME subtypes revealed an influence of CD163 on the mortality (dead yes or no) of RME tumor patients (p = 0.04) with an ODDS ratio of 0.634 and the event free survival time (p = 0.004) with an ODDS ratio of 0.497." (PMID 31239476, 2019). "Indeed, expression of the MGL receptor itself could be detected on CD163+ cells, suggesting that MGL+ myeloid cells are able to interact locally with MGL ligand+ tumor cells." (PMID 30761272, 2019). "However, this analysis shows also that CD163 negative cells within the tumor upregulate PDL1 after treatment, suggesting the instauration of additional mechanisms of immune evasion." (PMID 31214178, 2019). "In a single region of interest, among other cell types, tumor cells (Keratin+), T-helper cells (CD3+CD4+), cytotoxic T cells (CD3+CD8+), regulatory T cells (CD3+FOXP3+), HLA-DR+ macrophages (CD68+HLA-DR+), CD163+ macrophages (CD68+CD163+), and CD11c+ macrophages (CD68+CD11c+), were identified." (PMID 31736961, 2019). "These MØs express CD163 and M2-specific markers (increased expression of FOLR2 and MAF and reduced expression of ActA), and show an upregulated expression of different factors that favour tumour progression (including, among others, IL-10, TGF-β, IL-6, IL-8, IDO1, COX2 and GAL-1)." (PMID 31337120, 2019). "Interestingly, the antibodies to HIF1A and LGMN also labeled some tumor cells, whereas anti-CD163 and anti-CD68 did not." (PMID 31434729, 2019). "Indeed, prolonged interactions between stromal TAM (mainly CD163+ CD206+) and CD8 tumor-infiltrating lymphocytes (TILs) observed by dynamic imaging microscopy, are limiting CD8 T cell motility and their consecutive access to both human lung squamous cell carcinomas and mouse MMTV-PyMT tumors." (PMID 31766350, 2019).
tumor (continued). "The expression of CD163 was significantly associated with the clinical stage, perineural invasion, and distant metastasis of SACC (P < 0.05), whereas not with age, gender, tumor site, and tumor histotype (P > 0.05)." (PMID 31024838, 2019). "Therefore, the significant infiltration of CD163+ TAMs in PD-L1 IC- and TC- positive ICC may also be a consequence of immune reactions to tumor." (PMID 30885276, 2019). "CD163 was in both CDDP treated conditions higher expressed than in the low or high DFO treated conditions (DFO 10 μM, ∆0.3%; DFO 100 μM, ∆0.4%) compared with conditions with similar apoptotic tumor cell fraction and lower DFO concentration (CDDP 10 μM; DFO 10 μM + CDDP 10 μM)." (PMID 31413815, 2019). "Interestingly, OG treatment significantly increased the amount of F4/80+ macrophages, whereas it decreased the amount of CD11b+ myeloid cells and CD163+ macrophages in CAF-involved PDAC tumors, suggesting that OG suppressed tumor-infiltrating M2-macrophages that contributed to tumor promotion." (PMID 31905895, 2019). "In addition, CD163 expression was not elevated in tumor-bearing HSC-NOG-hIL-6 Tg mice (data not shown), and there were no transcripts of VEGF and IL-10 in splenic monocytes in HSC-NOG-hIL-6 Tg mice." (PMID 29456539, 2018). "In silico analysis confirmed that the expression of CXCR4 in the primary tumor significantly correlated not only with the expression of its ligand CXCL12 (Spearman's coefficient, rs = 0.4920) but also with the expression of VIM (rs = 0.4779) and CD163 (rs = 0.4853)." (PMID 29849822, 2018). "This was reflected by the correlation of PAR-1 gene expression with stroma markers like CD163, CD31 and vimentin, and ECM proteins like collagen and fibronectin, as well as by a significant increase in the intensity of PAR-1 staining in stromal cells of tumor tissue compared with normal lung tissue." (PMID 28173772, 2017). "The major population of TAMs is composed of CD163+ M2 polarized macrophages, and anti-tumor agents (e.g., IFN-α, IFN-β, or IFN-γ) could activate TAMs, which, once activated, could increase serum soluble (s)CD163 and release various autoimmune related chemokines such as CXCL5." (PMID 29050354, 2017). "Also in this type of analyses, the homogeneous distribution in both tumor regions (i.e., combined CD8+/CD163+ high and/or low cell densities in both TC and IM; HH/HH, LL/LL, HH/LL and LL/HH), could not significantly discriminate for DFS or OS." (PMID 28428887, 2017). "Furthermore, PD-L1 expression co-localized with CD68 and CD163, suggesting that in this case PD-L1 is primarily expressed by myeloid cells rather than tumor cells." (PMID 28344870, 2017). "Although CD163 expression in MNN-45 was markedly weak in vitro compared with SGC-7901, this difference was not obviously in vivo, hinting tumor microenvironment might be involved in the regulation of CD163." (PMID 29152078, 2017). "Our data suggest that the CD163-positive embedded stromal cells likely have a role in sustaining the aggressiveness of cancer cells, but the presence of pro-tumor macrophages alone may not be sufficient to affect the outcome of TNBC patients." (PMID 28721387, 2016). "Moreover, AXL was significantly co-expressed with genes associated with M2 macrophages, and positively correlated with the infiltration of CD163-positive M2 cells, suggesting an important relationship between AXL-expressing cells and TAMs with pro-tumor activity in a subgroup of TNBC." (PMID 28721387, 2016). "Of note, the CD163-positive macrophages may be more suitable to identify the TAMs than the CD68-positive macrophages in OSCC and the infiltration of CD163-positive macrophages in tumor may be more important for tumor progression." (PMID 26769084, 2016).
tumor (continued). "To study the inflammatory cell infiltration, we quantified the average densities of CD68+ macrophages (pan macrophage marker), CD163+ macrophages (M2, tumor promoting macrophage marker), and toluidine blue+ mast cells in the surrounding tumor bearing prostate tissue (TINT) of all tumor types." (PMID 26536349, 2015). "While the TAMs function to antagonize the anti-tumor effect of oncolytic viruses in GBMs, the CD68+ population may clear the apoptotic cancer cells in response to oncolytic treatment, whereas the CD163+ population may promote the growth of the remaining uninfected cancer cells." (PMID 24675569, 2014). "However, CD163 may be a superior marker of TAMs due to its higher specificity, as compared to CD68, for M2 macrophages, which are involved in tumor angiogenesis and progression." (PMID 24489836, 2014). "TAMs in murine tumor models are mainly from bone marrow and this might be a reason that no CD163 expression is detected in TAMs in murine tumor model." (PMID 24738052, 2014). "Interestingly, only invasive EMPD possessed substantial numbers of CD163+ M2 macrophages and MMP-9+ cells, B7H1+ cells, and ARG1+ cells around the tumor, whereas few CD163+ M2 macrophages, MMP-9+ cells, B7H1+ cells, and ARG1+ cells were observed in noninvasive EMPD." (PMID 23606867, 2013). "Together, the vaccine program may enhance antigen presentation and myeloid polarization (↑CD86/CD163), followed by Th1/Th17-skewed adaptive responses (↑IFN-γ, ↑IL-17), B-cell activation/anti–PD-L1 antibodies, and CD8+ CTL cytotoxicity, consistent with tumor control." (PMID 41455906, 2025). "Notably, in some peripheral tumor zones, CD163+ TAMs were entirely absent in several visual fields." (PMID 40843751, 2025). "Moreover, miR‐210‐3p inhibitor‐treated tumor spheroids notably promote monocyte phenotypic skewing towards M1 polarized macrophages compared to control inhibitor transfected spheroids, as evident from the increased expression of CD80, CD86, iNOS and decreased expression of CD206 and CD163." (PMID 35658112, 2024). "After TFF3 depletion, the expression of M2 markers (CD163, CD206, ARG-1, and IL-10) and S100A4 and S100A8 were remarkably downregulated, which confirmed our hypotheses that iCCA cells induce the M2 phenotype and pro-tumor polarization of resident macrophages by secreting TFF proteins." (PMID 39256888, 2024). "Thus, to test for relationships between K17 expression the tumor inflammatory microenvironment, we analyzed intratumoral and peritumoral CD8+ T cells, CD4+ T cells, CD16+/CD163− tumor-targeting (M1) macrophages and CD16+/CD163+ tumor promoting (M2) immune cells ratios across all cases." (PMID 38730319, 2024). "The findings revealed that the SNHG17 sh1 group had a lower level of CD163+ macrophage infiltration and fewer Ki-67-positive cells compared with the shNC group, demonstrating that SNHG17 knockdown could reduce the polarization of pro-tumor macrophages and suppress tumor proliferation in vivo." (PMID 38098044, 2023). "In addition, there was no direct relationship of CD163 protein expression with patients’ age, gender, tumor location, tumor diameter, degree of differentiation, TNM stage, presence/absence of signet-ring cells, and presence/absence of neural and vascular invasion (all P > 0.05)." (PMID 36859111, 2023). "Moreover, we developed a three-tiered integrated risk stratification model incorporating mitotic count, density of Ki-67+ and CD163+ cells, and MTOR mutation to more accurately identify SFT patients of primary non-CNS and CNS SFTs with negative tumor margins (NTM) at high risk for tumor progression." (PMID 37980418, 2023). "Additionally, higher infiltration levels of FOXP3+ Treg lymphocytes and CD163+ M2-like macrophages were found in the tumor microenvironment of RS compared to that of CLL, suggesting an enhanced immune suppression and resistance against adaptive immunity that promote tumor growth and progression." (PMID 36831361, 2023).
tumor (continued). "PD-L1 positivity (expression in >1% of tumour cells) was more frequent in ulcerated tumours than in nonulcerated tumours, and a positive correlation was found between the number of intratumoural CD11c+ and CD163+ cells and the frequency of PD-L1 expression of tumour cells." (PMID 37372432, 2023). "Finally, the NB tumours as a whole showed a trend for lower infiltration of T cells within the TME (e.g., CD8+ cells), while macrophages with noninflammatory phenotype (M2) were abundant (assayed by probing for CD163), suggesting an overall immunosuppressive environment." (PMID 37887559, 2023). "The univariate and multivariate analyses revealed that individual expression of EMR1-TC, CD68, and CD163 in tumor centers could not notably predict RFS or OS, but combined EMR1-TC+CD68+CD163+ expression in the tumor center area significantly correlated with worse RFS in CRC." (PMID 36551877, 2022). "Third, other immune cells, such as CD4+, CD163+, PD-1+, and PD-L1+ TILs, were not evaluated in the present study, which could be helpful for a comprehensive understanding of the relationship between systemic inflammation and the tumor microenvironment." (PMID 35915403, 2022). "Recent reports demonstrated HL patients with the highest M2 TAM count, measured using CD163 or CD68/CD163 as M2 polarization markers, had a significantly reduced disease-free survival (DFS), PFS and OS, further confirming M2 TAM could support tumor progression and immune escape." (PMID 34298810, 2021). "Notably, CD163+ infiltrations do not correlate with age and tumor size." (PMID 32344648, 2020). "However, tumor cell lines do not express CD163, even after stimulation with macrophage activating cytokines, so it has been hypothesized that tumor cells fuse with macrophages becoming more genetically unstable and aggressive." (PMID 32328462, 2020). "CD163+ tumor-associated macrophage (TAM) infiltration in tumor stroma is also of clinical interest as it is strongly associated with TNBC and is associated with poorer survival in TNBC with low TIL levels, though the role of CD163+ TAM infiltration in MBC has not been examined." (PMID 31937323, 2020). "In the paradigm of full differentiation and polarization by tumor cells alone, our results do not support a clear role for TGFα in polarization, as the primary effect of inhibiting TGFα is the loss of CD68+ macrophages rather than a shift in the percentage of CD163+ macrophages." (PMID 33069212, 2020). "Since PD-L1 was enriched in the adjacent stroma rather than in the tumor nest, to systematically analyze the TIME in PESCCs, where PD-L1 expression is enriched, we performed H&E staining and IHC analysis of CD4+ and CD8+ TILs and CD163+ tumor-associated macrophages (TAMs) in all 81 patients." (PMID 33457428, 2020). "Moreover, a high proportion of CD204+/CD163+ macrophages, as well as increasing levels of IL-6, IL-10, VEGF, and MCP-1 secretion by GC-MSC-treated macrophages, synergistically revealed a potent role of GC-MSCs in polarizing macrophages into a pro-tumor (M2) phenotype." (PMID 31801938, 2019). "Hence, 45 patient samples with PD-L1 positive (n = 23) or PD-L1 negative (n = 22) expression in tumor cells were stained for CD11c and CD163 and three different populations could be detected, i.e., CD163+CD11c−, CD163+CD11c+ and CD163-CD11c+." (PMID 31581535, 2019). "In addition, the interaction of Paget cells with other cells, such as LECs and CD163+Arg1+ macrophages in a tumor through the CXCR4–SDF-1 signaling and RANKL–RANK signaling, respectively, could establish a favorable tumor microenvironment to promote metastasis of Paget cells." (PMID 29503810, 2018). "Moreover, treatment with cHL cell SN conserved and enhanced the MΦ-2 phenotype in MΦM-CSF, as also demonstrated by the upregulation of CD163 known to promote an anti-inflammatory microenvironment and of CD206, which acts pro-angiogenic and thus might promote tumor growth." (PMID 25470820, 2014).
tumor (continued). "The CD163/CD11c expression ration in OSCC Biopsy Specimens (mean 3.87), in OSCC Resection samples without IT (mean 3.10) and in Tumor Resections after IT (mean 1.27) was each significantly (p ≤ 0.036) higher compared to Healthy Controls (mean 0.22)." (PMID 40297579, 2025). "Despite M2 macrophages’ similar tumor-promoting role, Rnaseh2c-cKO did not affect M1 (CD80, CD86) or M2 (CD163, ARG1) marker expression in mouse HCC-infiltrating macrophages." (PMID 41361104, 2025). "While our study did not specifically evaluate CD163+ TAMs, the dominant presence of CD204 TAMs suggests a comparable immunosuppressive role within the canine tumor microenvironment, mirroring the immunosuppressive niche described in human." (PMID 41375061, 2025). "Expression of CD163, CD209 and CD86 markers was not affected by the presence of tumor cells or by chemotherapeutic treatments, doxorubicin or epirubicin." (PMID 41009763, 2025). "A lower percentage of CD163+ cells was observed in tumor, stroma and total in MPR than non-MPR (percentage: tumor, p=0.041, stroma, p=0.001, total, p=0.000)." (PMID 39931056, 2025). "We noticed that in all three cases, nearly all macrophages displayed CD68+/CD163+ M2-like phenotype and no VSIG4 co-expression with CD19+ tumor cells or CD31+ endothelial cells." (PMID 40539047, 2025). "In contrast, we found no disparities in the expression of the markers CD68, CD163, and CD86 within the tumor nest across the entire cohort." (PMID 40510346, 2025). "However, since our patient had positivity for both CD68 and CD163, which is considered to indicate poor prognosis and since the patient requested postoperative adjuvant radiotherapy, we irradiated the whole breast on the affected side, without subsequent dosing in the tumor bed area." (PMID 41256322, 2025). "Our results confirmed that B4GALNT1 depletion significantly reduced tumor weight (p < 0.05), and the absence of B4GALNT1 led to a reduction in CD4 + T cells and CD163 + TAMs." (PMID 39616302, 2024). "Immunostains revealed the tumor cells to be positive for CD31, CD68, CD163, and CD34 (focal), whereas CD8 and CD 21 were negative." (PMID 38824259, 2024). "Next, we analyzed the presence of CD68 and CD163 (expressed by monocytes and Kupffer cells) and CD56 (expressed by NK cells) within the tumor and the surrounding nontumorous tissue." (PMID 38611048, 2024). "Although immunosuppressive CD163+ M2 macrophages and MMP9+ cells were detected, these cells were predominantly located around the remaining tumor cells rather than infiltrating the tumor like cytotoxic T cells." (PMID 39407789, 2024). "Compared with the non-responded tumors, it seemed that the responded tumor was infiltrated with more CD8+ T cells, less CD4+ T cells, less CD19+ B cells, and less CD163+ M2 macrophages." (PMID 38637495, 2024). "Markers for M2 macrophages, including CD68, CD163, and CD206, were found to be higher in lung tumor tissues compared to adjacent non-tumor lung tissues, regardless of histological types, including AC and SCC." (PMID 38791954, 2024). "The “repellency” of macrophages to T cells was also observed on tissue sections, as quantification of macrophage (CD163) and T cell (CD3) signals in tumor parenchyma demonstrated their negative correlation." (PMID 38896792, 2024). "In the mIHC analysis, compared to non-responded tumor, it seemed that responded tumor was infiltrated with more CD8+ T cells, and less CD4+ T cells, CD19+ B cells and CD163+ M2 macrophages." (PMID 38637495, 2024). "More specifically, in densely cellular tumor regions, P2RY12+ microglia were absent when tumors harbor high abundance of CD163+ macrophages." (PMID 39352749, 2024). "Subsequently, pathological biopsy of the lymph nodes revealed high expression of CD163, CD68, S100, Lys and CD34 in the tumor cells and no expression of CD1a and CD207, confirming this rare clinical diagnosis." (PMID 36969238, 2023).